HSP90AA4P (heat shock protein 90 alpha family class A member 4, pseudogene)
Description:
Putative molecular chaperone that may promote the maturation, structural maintenance and proper regulation of specific target proteins.
Synonyms: formerly HSPCAL2
Gene: Processed pseudogene on chromosome 4 (189,472,965 to 189,475,192, forward strand). Ensembl gene ENSG00000205100.
Subcellular location: Cytoplasm